RNU6-588P (RNA, U6 small nuclear 588, pseudogene)
Gene: Small nuclear RNA gene on chromosome 5 (149,606,637 to 149,606,741, reverse strand). Ensembl gene ENSG00000222213.
Homologues: Orthologues: chimpanzee U6 (98% identical), macaque U6 (94% identical), guinea pig U6 (70% identical), dog U6 (65% identical). Paralogues in human: RNU6-1152P (83% identical), RNU6-1011P (82% identical), RNU6-1029P (82% identical), RNU6-1038P (82% identical), RNU6-1117P (82% identical), RNU6-1122P (82% identical), RNU6-820P (82% identical), RNU6-842P (82% identical), RNU6-1155P (81% identical), RNU6-211P (81% identical), RNU6-589P (81% identical), RNU6-812P (81% identical), and 1285 more.